FUCA1 (alpha-L-fucosidase 1)
Diseases named in the same sentence as FUCA1 in open-access papers (continued):
Sharing a sentence is not in itself a finding about the gene and the disease.
breast carcinoma (continued). "In contrast, lower FUCA1 expression levels were detected in advanced-stage (stage 4) breast cancers (indicated by a red arrow)." (PMID 26204487, 2015). "In this study, we evaluated FUCA1 expression in breast cancer tissue samples from patients with different stage disease." (PMID 26204487, 2015). "α-L-fucosidase 1 (FUCA1) is a lysosomal enzyme that catalyzes the hydrolytic cleavage of the terminal fucose residue in breast cancer cells." (PMID 26204487, 2015). "In this study, the over-expression of FUCA1 was detected in early-stage breast cancer tissue from Asian patients." (PMID 26204487, 2015). "Lower FUCA1 expression was preferentially detected in tissues from patients with advanced-stage (stage 3 to 4) breast cancer." (PMID 26204487, 2015). "FUCA1 in glioblastoma multiforme, papillary thyroid cancer (PTCs) samples, and breast cancer." (PMID 37601653, 2023). "Additionally, overexpression of FUCA1 attenuates thyroid cancer cell motility, and FUCA1 stably depleted breast cancer cells develop increased proliferative and metastatic capabilities." (PMID 36864055, 2023). "In breast cancer, it has been proven that FUCA-1 has independent prognostic value." (PMID 31602256, 2019). "Furthermore, the analysis of a publically available database (Oncomine) shows that a lower expression of FUCA-1 mRNA is characteristic of histologically more invasive and aggressive breast cancer cell lines subtypes." (PMID 29632639, 2018). "Furthermore, FUCA-1 was shown to be up-regulated only in Luminal A breast cancer patients compared to basal-like breast cancer patients in a study of glycan-related gene expression profiling in breast cancer subtypes." (PMID 29632639, 2018). "This study shows that, within LN+ breast cancer patients, FUCA-1 is able to identify a sub-set of non recurrent patients characterized by the positive expression of FUCA-1 and that, within luminal B LN+ patients, the expression of FUCA-1 predicts longer cancer specific survival." (PMID 29632639, 2018). "However, our clinical observations indicated that FUCA1 was expressed at a lower level in advanced-stage breast cancer cells." (PMID 26204487, 2015). "FUCA1 was preferentially detected in early-stage breast cancer tissues." (PMID 26204487, 2015). "Thus, reduced expression of α-L-fucosidase 1 (FUCA1) and increased expression of α1,6-fucosyltransferase (FUT8) lead to an increase in α1,3-linked fucose in the Lewis X antigen (LeX) and core residues of α1,6-linked fucose in N-glycans in breast cancer." (PMID 39728102, 2024). "Additionally, FUCA1 could inhibit intercellular adhesion of breast cancer cells though down-regulating their CD44, CD15, and matrix metalloproteinases (MMP) -9 expression." (PMID 36046653, 2022). "Thus, expression levels of FUCA-1 may predict the prognosis of mammary tumors, CRC, neuroblastomas and thyroid tumors." (PMID 28404918, 2017). "The regulatory role of FUCA1 on two cancer stemness marker, CD44 and CD15, implies its potential function in recurrent of breast cancer." (PMID 36046653, 2022). "FUCA1 expression in breast cancer with lung metastasis lesion is lower than that of breast cancer without lung metastasis." (PMID 36046653, 2022).
lysosomal storage disease (10 papers, 2019 to 2026). A metabolic disorder caused by mutations in proteins critical for lysosomal function, including lysosomal enzymes, lysosomal integral membrane proteins, and proteins involved in the post-translational modification and trafficking of lysosomal proteins. "In fact, isolated cases with GP hypointensities consistent with iron excess are known in at least 17 distinct genes, including AP4M1 and AP4S1, which, like FUCA1, GLB1, and TPP1, are involved in lysosomal disorders." (PMID 36233161, 2022).
glioma (7 papers, 2021 to 2025). A benign or malignant brain and spinal cord tumor that arises from glial cells (astrocytes, oligodendrocytes, ependymal cells). "Moreover, FUCA1 has also been associated with suppressive TME in that FUCA1 depletion reduces tumor associated macrophage (TAM) recruitment to the tumor site in glioma." (PMID 36864055, 2023). "The inhibition of FUCA1 suppressed glioma growth in vitro and in vivo, promoting autophagy through the formation of large acidic vacuoles and by lowering levels of tumor-infiltrating macrophages." (PMID 37601653, 2023). "Lower levels of tumor-infiltrating macrophages, including CD68+ (~30%), F4/80+ (~50%), and CD11c+ macrophages (~50%), were identified in FUCA1-downregulated glioma tissues, and CCL2/CCL5 neutralizing Abs blocked this effect." (PMID 34071306, 2021). "However, downregulation of FUCA1 expression inhibited glioma progression by enhancing autophagy and suppressing macrophage infiltration." (PMID 40487392, 2025). "Silencing of lysosome enzyme alpha-l-fucosidase 1 (FUCA1) impedes U87 and U251 glioma cell proliferation, whereas the growth inhibition appears less significant when the cells are co-incubating with 3-MA." (PMID 34671362, 2021).
thyroid cancer (7 papers, 2017 to 2024). "FUCA-1 mRNA expression from tissue samples and cell lines and protein expression levels and enzyme activity in thyroid cancer cell lines paralleled those of IHC staining." (PMID 28404918, 2017). "The correlation between low FUCA-1 expression and invasive properties of the thyroid cancer cells was confirmed by silencing FUCA-1 in the less aggressive papillary TPC-1 cells, which constitutively expressed high levels of FUCA-1." (PMID 28404918, 2017). "We next examined the FUCA-1-specific proteins in thyroid cancer cell lines (TPC-1 and BCPAP of PTC and 8505C and CAL62 of ATC)." (PMID 28404918, 2017). "This is the first report indicating that the down-regulation of FUCA-1 is related to the increased aggressiveness of thyroid cancer." (PMID 28404918, 2017). "The differences in FUCA-1 expression found by us between PTCs and ATCs have been confirmed by examining a panel of thyroid cancer cell lines derived from different PTCs and ATCs." (PMID 28404918, 2017). "These experiments confirmed the idea that FUCA-1 plays a role in attenuating the aggressive behavior of invasive and metastatic thyroid cancer cells." (PMID 28404918, 2017). "To test whether FUCA-1 expression is higher in more differentiated thyroid cancers, when compared with the more aggressive, undifferentiated thyroid cancers, we analyzed also human thyroid cell lines derived from patients with PTC or ATC." (PMID 28404918, 2017). "Therefore, our data indicate for the first time that the decrease of FUCA-1 levels could be regarded as a potential marker for aggressive thyroid cancer cell types." (PMID 28404918, 2017). "On the other hand, other studies have demonstrated that overexpression of FUCA1 does not affect the clonogenic potential of thyroid cancer or normal cells." (PMID 39123480, 2024).
colorectal cancer (5 papers, 2013 to 2023). A primary or metastatic malignant neoplasm that affects the colon or rectum. "The aim of this work was to extend the knowledge about tissue alpha-l-fucosidase in colorectal cancer by quantifying the expression of its encoding gene FUCA1 in tumors and healthy mucosa." (PMID 23965968, 2013). "Decreased FUCA1 expression has been observed in colorectal cancer, hepatocellular carcinoma, and anaplastic thyroid cancer (ATCs) samples." (PMID 37601653, 2023). "A decreased expression of the FUCA-1- gene was also found in human colorectal carcinomas, compared to normal mucosa and a gradual decrement in FUCA-1 expression was observed with progression of the disease from earlier to advanced stages." (PMID 29632639, 2018). "A decreased expression of the FUCA1 gene was also found in human colorectal carcinomas compared to normal mucosa and further a gradual decrease in FUCA-1 expression was observed with progression of the disease from early to advanced stages." (PMID 28404918, 2017). "FUCA1 in colorectal cancer, HCC, and anaplastic thyroid cancer (ATCs) samples." (PMID 37601653, 2023). "Furthermore, decreased expression of the FUCA-1 gene was also found in human colorectal carcinomas compared with normal counterparts." (PMID 31602256, 2019). "Previous observations, regarding the role of fucosylation in cancer, indicated that the human lysosomal enzyme α-L-fucosidase-1 (FUCA-1, EC number 3.2.1.51) is down-regulated in highly aggressive human tumors such as neuroblastomas, breast, and colorectal cancers." (PMID 29632639, 2018). "Moreover, a future study exploring the utility of FUCA1 gene as a prognostic marker for colorectal cancer is warranted." (PMID 23965968, 2013). "Our results demonstrated diminished FUCA1 mRNA levels in tumors, suggesting that expression of tissue alpha-l-fucosidase could be regulated at transcriptional level in colorectal cancer." (PMID 23965968, 2013).
anaplastic thyroid cancer (3 papers, 2017 to 2024). "FUCA-1 gene expression tested by Real Time PCR showed that the anaplastic thyroid cancer cell lines analyzed displayed lower levels of the FUCA-1 mRNA, compared with the two papillary cancer cell lines analyzed (TPC-1 and BCPAP)." (PMID 28404918, 2017). "FUCA-1 expression of various thyroid normal and cancer tissues assayed by immunohistochemical (IHC) staining was high in normal thyroids and papillary thyroid carcinomas (PTC), whereas it progressively decreased in poorly differentiated, metastatic and anaplastic thyroid carcinomas (ATC)." (PMID 28404918, 2017).
neuroblastoma (3 papers, 2017 to 2025). Neuroblastoma (NB) is the most common solid, extracranial childhood tumor. "We therefore tested cross-reactivity against both orthologs by western blotting using lysates from transfected mouse neuroblastoma Neu2A cells expressing either the human construct (pcDNA3.1Hygro(+)-FUCA1) or the murine construct (pcDNA3.1Hygro(+)-Fuca1)." (PMID 40940767, 2025).
papillary thyroid cancer (3 papers, 2017 to 2024). "On the contrary, silencing of FUCA-1 in the papillary thyroid cancer TPC-1 cell line, that expressed high levels of the enzyme, increased its invasive behavior in vitro." (PMID 28404918, 2017). "We report here a significantly lower expression of FUCA-1 in anaplastic thyroid tumors when compared with that of papillary thyroid carcinomas." (PMID 28404918, 2017). "Furthermore, we performed preliminary experiments to silence the FUCA-1 gene in the TPC-1 papillary thyroid cancer cell line." (PMID 28404918, 2017).
renal clear cell carcinoma (3 papers, 2021 to 2023). "In this study, M2 macrophages can up-regulate the expression of FUCA1, but its actual expression in renal clear cell carcinoma is down-regulated." (PMID 37361571, 2023).
breast tumor (2 papers, 2015 to 2021). "All these observations indicate that high FUCA1 expression could alter the composition and decrease the quantity of cell surface fucosylation-associated molecules, thereby limiting the invasiveness of cancer cells in early-stage breast tumors." (PMID 26204487, 2015). "FUCA1 mRNA levels were detected by real-time PCR, and there was a greater than 139-fold increase in FUCA1 mRNA expression in breast tumor samples compared with normal breast tissue samples (*P = 0.005, n = 236)." (PMID 26204487, 2015).
colorectal adenocarcinoma (2 papers, 2015 to 2021). The most common type of colorectal carcinoma. "In another study, colorectal adenocarcinoma patients showed significant decrease in FUCA1 activity with the progression of the disease from early to advanced stages." (PMID 34703796, 2021). "Similar observations were reported in patients with colorectal adenocarcinoma showing significant decrease in FUCA1 activity in malignant tissue compared to healthy colonic mucosa in the same patients." (PMID 34703796, 2021). "Similar observations in patients with colorectal adenocarcinoma have revealed a significant decrease in FUCA1 activity in malignant tissue compared with healthy colonic mucosa in the same patient." (PMID 26204487, 2015).
lung carcinoma (2 papers, 2018 to 2025). "Expression of FUCA1 induced apoptosis in renal tumor cells, and knockdown of FUCA1 enhanced the proliferation of lung cancer cells." (PMID 40487392, 2025). "In lung cancer, FUCA1 can inhibit EGFR signaling and its downstream signaling by inhibiting AKT phosphorylation." (PMID 40487392, 2025). "There is little knowledge on the relationship between FUCA1 and lung cancer." (PMID 30619732, 2018).
renal carcinoma (2 papers, 2024 to 2025). A carcinoma arising from the epithelium of the renal parenchyma or the renal pelvis. "The expression of FUCA1, NAT8 and SMIM24 in renal carcinoma cell lines is lower than those in renal tubular epithelial cells and suggests a better prognosis." (PMID 38517387, 2024).
Alzheimer disease (1 paper, 2024). A progressive, neurodegenerative disease characterized by loss of function and death of nerve cells in several areas of the brain leading to loss of cognitive function such as memory and language. "The most intriguing examples include GRN and FUCA1, as their loss of functions directly causes lysosomal dysregulation and neuroinflammation, accompanied by neurodegenerative disorders such as Alzheimer’s disease (AD) and frontotemporal dementia (FTD)." (PMID 38507437, 2024).
bladder cancer (1 paper, 2017). "These included proteins previously associated with bladder cancer and also additional novel such as PGRMC1, FUCA1, BROX and PSMD12, which were further confirmed by immunohistochemistry." (PMID 29050215, 2017).
colon cancer (1 paper, 2018). "The role of FUCA-1 in reducing invasiveness in breast and colon cancer could be explained by FUCA-1 mediated decrease in the composition and quantity of cell surface fucosylation-associated molecules." (PMID 29632639, 2018).
Colorectal Tumors (1 paper, 2013). "In conclusion, our present data demonstrate a reduction in the mRNA of FUCA1 in colorectal tumors, suggesting that the expression of tissue alpha-l-fucosidase could be regulated at the transcriptional level." (PMID 23965968, 2013).
Dystonia (1 paper, 2022). An abnormally increased muscular tone that causes fixed abnormal postures. "Of those, five patients presented MDs such as dystonia or parkinsonism, spasticity, and suspicion of brain iron deposits or GP hypointensities; they were associated with variants in FBXO7, FUCA1, GLB1, TPP1, and KIF1A." (PMID 36233161, 2022).
Encephalopathy (1 paper, 2022). Encephalopathy is a term that means brain disease, damage, or malfunction. "MD-137 (homozygous FUCA1 p.R47P) with a history of static encephalopathy, had a dystonic gait from 3 years old and presented GP T2W hypointensities from 10 years old." (PMID 36233161, 2022).
head and neck squamous cell carcinoma (1 paper, 2021). A squamous cell carcinoma that arises from any of the following anatomic sites: lip and oral cavity, nasal cavity, paranasal sinuses, pharynx, larynx, and salivary glands. "In the head and neck squamous cell carcinoma (HNSCC), primary tumors exhibiting higher FUCA1 expression are found to be significantly associated with worse patient survival." (PMID 34703796, 2021).
meningioma (1 paper, 2020). A generally slow growing tumor attached to the dura mater. "Proteins involved in neutrophil degranulation, such as ARSA, GCA, FUCA1, PRTN3, ELANE, MNDA, and LCN2, were identified uniquely or with differential abundance in male meningiomas." (PMID 32587372, 2020).
oral carcinoma (1 paper, 2021). "Therefore, we analyzed the association between mRNA levels of FUTs and FUCA1 with various clinico-pathological parameters of oral cancer patients." (PMID 34703796, 2021). "In this study, significant down regulation of FUTs and FUCA1 was observed in oral cancer tissues in comparison with adjacent normal tissues." (PMID 34703796, 2021). "However, to the best of our knowledge, no such studies have extensively analyzed the role of FUTs and FUCA1 in oral cancer progression." (PMID 34703796, 2021). "Therefore, the present investigation was aimed to evaluate the clinical significance of mRNA expressions of various fucosyltransferses (FUT3, FUT4, FUT5, FUT6, FUT8) and fucosidases (FUCA1) in oral cancer progression." (PMID 34703796, 2021). "In this study, we examined the mRNA expressions of fucosidase (FUCA1) and FUTs (FUTs (FUT3, FUT4, FUT5, FUT6, FUT8) in human oral cancer tissues." (PMID 34703796, 2021).
osteosarcoma (1 paper, 2021). A usually aggressive malignant bone-forming mesenchymal neoplasm, predominantly affecting adolescents and young adults. "Consistent with previous research, FUCA1 was distinctly correlated to osteosarcoma patients." (PMID 34630511, 2021).
renal cell carcinoma (1 paper, 2023). "The results showed that FUCA1 was down-regulated and SLC40A1, VSIG4, CRYBB1 and LIPA were up-regulated in renal cell carcinoma and 786-O, and the difference was statistically significant." (PMID 37361571, 2023).
thyroid (1 paper, 2017). "In order to better define the role of FUCA-1 in thyroid carcinogenesis, we stably transfected 8505C cells with α-L-fucosidase DNA." (PMID 28404918, 2017).
tongue cancer (1 paper, 2021). A malignant neoplasm affecting the tongue. "Overall, mRNA levels of all FUTs and FUCA1 were higher in tongue carcinoma patients in comparison with buccal carcinoma patients." (PMID 34703796, 2021). "Further, we have documented that the treatment of tobacco metabolites such as 4-NQO, NNK, Benzopyrene lead to the increase in FUT4, FUT5, FUT6, and FUCA1 transcripts in a dose dependent manner in treated tongue carcinoma cells." (PMID 34703796, 2021). "Analyzing the mRNA expression of FUTs and FUCA1 revealed that, mRNA levels of FUTs and FUCA1 were higher with significant up regulation of FUT4 and FUT8 in the tongue carcinoma patients as compared to the buccal carcinoma as a primary site of the disease." (PMID 34703796, 2021).
Tremor (1 paper, 2016). An unintentional, oscillating to-and-fro muscle movement about a joint axis. "From this age onwards, Fuca1-deficient mice became progressively inactive, avoided any type of movement, became ataxic and developed a massive tremor." (PMID 27491075, 2016).
triple-negative breast carcinoma (1 paper, 2015). An invasive breast carcinoma which is negative for expression of estrogen receptor (ER), progesterone receptor (PR), and human epidermal growth factor receptor 2 (HER2). "Statistical analysis revealed that lower FUCA1 levels significantly predicted an inferior overall survival rate among triple-negative breast cancer (TNBC) patients compared with non-TNBC patients (*P = 0.009)." (PMID 26204487, 2015).